CYP2C8 (cytochrome P450 family 2 subfamily C member 8)
Diseases named in the same sentence as CYP2C8 in open-access papers (continued):
Sharing a sentence is not in itself a finding about the gene and the disease.
tumor (28 papers, 2005 to 2025). "And, low expression of CYP2C8 in tumor tissues was linked to worse OS in HCC patients with median cut-off (log rank P = 0.018)." (PMID 30148168, 2018). "Considered above, we assumed that downregulation of CYP2A6 and CYP2C8 in tumor tissues is associated with worse clinicopathological characteristics in HCC patients." (PMID 30148168, 2018). "Our research demonstrated that CYP2C8 downregulation in tumor tissues was associated with advanced tumor phenotype and worse OS and RFS." (PMID 30148168, 2018). "Only the haplotype allele containing the CYP2C8*4 was associated with the tumour characteristics as presented above." (PMID 19935798, 2009). "Each copy of the CYP2C8/9 *1/*4/*1/*1 allele was associated with significantly lower risk for nodal involvement, while each copy of the CYP2C8/9 *3/*1/*2/*1 allele was associated with increased risk for nodal involvement in tumours larger than 20 mm." (PMID 19935798, 2009). "Significantly less node involvement (P=0.002) and fewer PR+ tumours (P=0.012) were associated with CYP2C8*4." (PMID 19935798, 2009). "Additionally, lower CYP2A6 and CYP2C8 are associated with advanced clinicopathological features including tumor staging, vascular invasion, intrahepatic metastasis, and high alpha fetoprotein (all P < 0.05)." (PMID 30148168, 2018). "Additionally, HCC patients with low CYP2A6 and CYP2C8 levels in tumor tissues had higher risk of vascular invasion, major portal vein invasion, and intrahepatic metastasis (all P < 0.05)." (PMID 30148168, 2018). "The associations between the CYP2C8/9 *1/*4/*1/*1 haplotype and CYP2C8/9 *3/*1/*2/*1 haplotypes and lymph node involvement was different depending on the invasive tumour size (exp(β)=0.33; Pinteraction=0.10 and exp(β)=3.2; Pinteraction=0.040, respectively, when entered into the same model)." (PMID 19935798, 2009). "The number of CYP2C8/9 *1/*4/*1/*1 copies was significantly associated with a decreased frequency for axillary lymph node involvement (odds ratio (OR) 0.40; 95% Confidence interval (CI) 0.22–0.74; P=0.003), adjusted for tumour size, histological grade, age at diagnosis, and ER and PR status." (PMID 19935798, 2009). "Only those tumour samples were considered to carry multiplication of CYP2C8 in which the CYP2C8*1 copy number was increased." (PMID 37686184, 2023). "In the TCGA database, low expression of CYP2C8, CYP2C9, and CYP2C19 in tumor tissue was associated with short median survival." (PMID 36557005, 2022). "CLEC1B, GYS2, and CYP2C8 were identified as tumor suppressors for the prognosis, however, EXO1 was determined to be an oncogene." (PMID 34950206, 2021). "Since drug metabolism mediated by tumor CYPs can be used as a marker for potential mechanism of drug resistance and/or an approach to achieve optimal chemotherapy, to upregulate CYP2C8 levels, and activations should be considered for HCC treatment strategy." (PMID 30148168, 2018). "In TCGA database, low expression of CYP2C8,CYP2C9, and CYP2C19 in tumor tissue was associated with a short median survival time (all crude P = 0.001, adjusted P = 0.004, P = 0.047, and P = 0.020, respectively)." (PMID 29479826, 2018). "In small tumours, angiogenesis is also a predictor of nodal status, and it is thus possible that women with the CYP2C8/9 *3/*1/*2/*1 genotype have tumours that are more likely to metastasise through increased angiogenesis." (PMID 19935798, 2009). "This is the first study to report an association between decreased odds for lymph node involvement and CYP2C8*4 and an over twofold increased odds for lymph node involvement among CYP2C8/9 *3/*1/*2/*1 carriers with invasive tumour sizes over 20 mm." (PMID 19935798, 2009). "Furthermore, the differential expression of the top five genes (C6, UGT2B7, SLC22A1, F11, and CYP2C8) in the RF model between normal and tumor tissues was validated using the GSE25097 and TCGA datasets." (PMID 39548390, 2024).
tumor (continued). "Furthermore, we validated the differential expression of the top five genes (C6, UGT2B7, SLC22A1, F11, and CYP2C8) between normal and tumor tissues using the GSE25097 and TCGA datasets." (PMID 39548390, 2024). "The multiplication of the CYP2C8*3 allele is not expected to increase paclitaxel-metabolizing activity of the tumour cells; therefore, the multiplication of the functional wild-type allele is reasonable to consider in a tumour." (PMID 37686184, 2023). "A further question was raised that the copy number alteration may extend beyond the CYP2C8 gene, and the alterations in tumour suppressor genes or oncogenes surrounding the CYP2C8 may also contribute to disease evolution." (PMID 37686184, 2023). "In addition, the low expression level of CYP2C8 was related to advanced clinicopathological features, including tumor stage and intrahepatic metastasis." (PMID 34950206, 2021). "Downregulation of CYP2A6 and CYP2C8 in tumor tissues links to poorer OS and RFS in HCC patients." (PMID 30148168, 2018). "Interestingly, in GSE36376 database, HCC patients with low CYP2A6 and CYP2C8 levels in tumor tissues suffered from more advanced edmondson grade and AJCC staging (all P < 0.05)." (PMID 30148168, 2018). "In GSE14520 dataset, we identified the fact that low expressions of four CYPs including CYP2A6, CYP2C8, CYP2E1, and CYP4A11 in tumor tissues were significantly associated with worse OS in HCC patients (log ranks P = 0.01, 0.006, 0.024, and 0.007, respectively)." (PMID 30148168, 2018). "Tumor size negatively correlated with CYP2C8 and CYP2C19 levels." (PMID 25526449, 2014). "It is possible that the association between CYP2C8 variations and cisplatin survival may not be direct, and other variables, such as the patient’s general health condition or the features of their tumor, may be responsible for this outcome." (PMID 37372990, 2023). "In the case of CYP2C8, however, increased expression in tumor tissue could be observed." (PMID 31309254, 2019). "The absence of a relative risk related to CYP2C8*3 did not vary depending on the tumor site." (PMID 23420707, 2012). "Whereas, to be tumor suppressors, ficolin 3 (FCN3), cytochrome P450 family 2 subfamily C member 8 (CYP2C8), and fructose-1,6-biphosphatase (FBP1) have been reported to be downregulated in HCC and inhibited the progression of HCC." (PMID 38664521, 2024). "Increased expression of CYP2C8 and/or CYP3A4 and the high paclitaxel-metabolizing activity of tumour cells are also assumed to be developed as a consequence of the multiplication of CYP copy numbers." (PMID 37686184, 2023). "For now, it is important to incorporate what is currently known about CYP3A4, CYP3A5, CYP2C8, and ABCB1 into the assessment of a patient when the mTOR pathway is a desired target in treating a tumor." (PMID 37240915, 2023). "Briefly, endothelial-specific expression of either CYP2C8 or CYP2J2 (Tie2-CYP2C8-Tr, Tie2-CYP2J2-Tr) accelerated the escape from tumor dormancy and extensive multi-organ metastasis." (PMID 33637672, 2021). "HCC patients with CYP2A6 and CYP2C8 low levels in tumor tissues suffered from poorer overall survival (OS) compared to those with high CYP2A6 and CYP2C8 in GSE14520 profile (log ranks P = 0.01 and P = 0.006, respectively)." (PMID 30148168, 2018). "In our study, we found that several CYPs including CYP1A2, CYP2A6, CYP2C8, CYP2C9, CYP2E1, CYP3A4, and CYP4A11 were all downregulated in tumor tissues in HCC patients." (PMID 30148168, 2018). "The GEP analysis showed that the down-regulated genes in tumor tissue were CYP3A4 in 56 patients (61%), CYP2C8 in 44 patients (48%), CYP2C19 in 30 patients (33%), CYP2D6 in 11 patients (12%), CYP3A5 in 7 patients (8%) and CYP1B1 in 2 patients (2%)." (PMID 29774122, 2018). "The genes found to be down-regulated in tumor tissue were CYP3A4 in 56 patients (61%), CYP2C8 in 44 patients (48%), CYP2C19 in 30 patients (33%), CYP2D6 in 11 patients (12%), CYP3A5 in 7 patients (8%) and CYP1B1 in 2 patients (2%)." (PMID 29774122, 2018).
tumor (continued). "Seven CYP450 genes including CYP1A2, CYP2A6, CYP2C8, CYP2C9, CYP2E1, CYP3A4, and CYP4A11 were downregulated in tumor tissues, which were validated in both GSE14520 and GSE36376." (PMID 30148168, 2018). "Looking closely at the SCC-820 genes that were frequently up-regulated or down-regulated in tumor tissue, especially those that were down-regulated—in addition to CYP3A4—both CYP2C8 and CYP2C19 were included in the top thirty genes." (PMID 29774122, 2018). "No significant changes in expression of AKR1B1, AKR1D1, AKR7A2, CBR1, CYP2C8, and CYP2C9 between tumor and control tissues were found." (PMID 25526449, 2014). "Furthermore, CYP2C8 and 2C9 protein levels positively correlated with Ki67 status, and CYP2J2 levels positively correlated with histological grade and tumor size." (PMID 25406731, 2014). "In conclusion, among other factors, the altered protein levels of certain CYPs (e.g. CYP2C8, CYP3A4 and CYP3A5) in colon mucosa might contribute to the development of neoplasia in the colon." (PMID 16281975, 2005). "In the primary tumour samples from non-responder patients (N = 9), copy number alterations in CYP2C8 and/or CYP3A4 were detected more frequently than in the samples from responders (N = 8) (non-responders 6/9 vs. responders 1/8, p = 0.0498, Fisher’s exact test)." (PMID 37686184, 2023). "Concentrations of Gamitrinib that trigger tumor cell killing (IC50 ~1-4 μM) do not affect cytochrome P450 isoforms CYP1A2, CYP2A6, CYP2B6, CYP2C8 or ion channel conductance (Nav1.5, Kv4.3/KChIP2, Cav1.2, Kv1.5, KCNQ1/mink, HCN4, Kir2)." (PMID 35129069, 2022). "Patients without preoperative treatment and at least one copy of CYP2C8*3, CYP2C9*2, or CYP2C9*3 did not significantly differ with respect to age at diagnosis, invasive tumour size, axillary node status, histological grade, and ER or PR status when compared with the wild-type for each SNP." (PMID 19935798, 2009).
peripheral neuropathy (3 papers, 2016 to 2025). A disorder affecting the peripheral nervous system. "CYP2C8 rs10509681 was present at frequencies comparable to European populations and is associated with an increased risk of taxane-induced peripheral neuropathy." (PMID 41300713, 2025). "The development of paclitaxel-induced peripheral neuropathy has been described from several groups to be primarily influenced by drug exposure and patient polymorphisms in CYP2C8 gene." (PMID 27304055, 2016). "Specifically the CYP2C8*3 polymorphism has been associated to peripheral neuropathy risk due to decreased metabolism and elimination, which leads to increased toxicity and efficacy mainly in African-Americans." (PMID 27304055, 2016). "CYP2C8*3 is associated with an increase in peripheral neuropathy in patients treated with PAC, presumably a result of slower PAC elimination by CYP2C8*3." (PMID 31540428, 2019).
adenocarcinoma (1 paper, 2023). A common cancer characterized by the presence of malignant glandular cells. "In treatment naïve adenocarcinoma samples, the copy number multiplication of paclitaxel-metabolizing CYP2C8 and/or CYP3A4 was more prevalent in non-responder patients with progressive disease/exit than in responders with complete remission." (PMID 37686184, 2023).
colon (1 paper, 2020). "Our results indicate a suppression of enzymes involved in various stages of carcinogen breakdown including CYP2C8, CYP4F12, GSTA1, and UGT1A within right colon tumors." (PMID 32293332, 2020).
heart disease (1 paper, 2022). "These include clinically important interactions between CYP2C8 substrates and heart disease medications gemfibrozil and clopidogrel, due to time-dependent inhibition or mechanism-based inactivation of CYP2C8 by the acyl β–d–glucuronide (acyl glucuronide) metabolites of these drugs." (PMID 36139056, 2022).
infection (1 paper, 2021). The state of being infected such as from the introduction of a foreign agent such as serum, vaccine, antigenic substance or organism. "More specifically, it was assessed if CYP2C8*2 and CYP2C8*3 carriers were at increased risk of new and/or recrudescent infections during the 42-day follow-up period, and if CYP2C8*2 and CYP2C8*3 carriers were at increased risk of experiencing adverse events after AS–AQ treatment." (PMID 33588856, 2021).
retinopathy (1 paper, 2019). "In CYP2C8-overexpressing mice fed a ω-3 PUFA diet, CYP inhibition suppressed retinal neovascularization and choroidal neovascularization while sEH inhibition increased oxygen-induced retinopathy and choroidal neovascularization." (PMID 31333461, 2019).
CYP2C8 also shares sentences with these, for which no sentence is quoted: myocardial infarction (3 papers); depression (2); gestational diabetes mellitus (2); Obesity (2); primary biliary cholangitis (2); type 2 diabetes (2); allergies (1); Alzheimer disease (1); autoimmune hepatitis (1); bladder urothelial carcinoma (1); cardiomyopathy (1); cardiovascular disease (1); chronic myeloid leukemia (1); degenerative diseases (1); dementia (1); diabetic retinopathy (1); endometriosis (1); epilepsy (1); esophageal carcinoma (1); esophageal squamous cell carcinoma (1); fibrosis (1); heart failure (1); hepatitis C (1); hereditary ataxia (1); hyperlipidemia (1); ischemic stroke (1); liver failure (1); medulloblastoma (1); mucositis (1); multiple myeloma (1).
A further 13 diseases each share a sentence with CYP2C8 in 1 paper.